CRP (C-reactive protein)
Diseases named in the same sentence as CRP in open-access papers (continued):
Sharing a sentence is not in itself a finding about the gene and the disease.
Sepsis (continued). "All 303 neonates with the diagnosis of clinical sepsis, underwent CRP determination where positive results were reported in 136 (45%) of cases." (PMID 30069260, 2018). "Several studies have confirmed that presepsin is a more specific and sensitive marker for the diagnosis of sepsis compared with C-reactive protein (CRP), interleukin-6 (IL-6), or procalcitonin (PCT)." (PMID 30470216, 2018). "CRP and leucocyte are generally regarded as useful markers for the diagnosis of sepsis, and are usually used together with blood cultures." (PMID 29995751, 2018). "The most pronounced change was the increased levels of several acute phase proteins, such as serum amyloid A-1, serum amyloid A-2 and c-reactive protein (CRP), all over 500-fold more abundant in the sepsis patients." (PMID 29511047, 2018). "The IL-6, WBC and C-reactive protein (CRP) levels of the sepsis group and SIRS group were significantly higher than those of the control group (P < 0.05)." (PMID 29760745, 2018). "Compared with other sepsis markers, including C-reactive protein (CRP) and PCT, P-SEP appears to have a better specificity and sensitivity for the diagnosis of sepsis, as blood levels of P-SEP in patients with injuries or burns are almost normal." (PMID 30647802, 2018). "Many studies have assessed the use of CRP for the diagnosis of early-onset sepsis in term and late-preterm infants." (PMID 29382319, 2018). "Many studies have found that the level of presepsin in patients with sepsis is significantly higher than in healthy infants, and over time, similar to CRP and PCT, it decreases with antibiotic treatment." (PMID 30463590, 2018). "In our study, it was striking that the median CRP 2 levels for all types of sepsis were found to be lower than the initial values." (PMID 30068303, 2018). "WBC count, CRP, and PCT are widely used in clinical practice as diagnostic and prognostic biomarkers of inflammation, infection, and sepsis." (PMID 29861795, 2018). "At our center, we take CRP as a biomarker of sepsis and its serial decline is taken as laboratory evidence of improvement." (PMID 29950162, 2018). "Clinically, three inflammatory biomarkers have been applied in patients with sepsis: C-reactive protein (CRP), procalcitonin, and presepsin." (PMID 29364941, 2018). "At initial sepsis work-up (T0), combining the CBC and CRP offered the highest sensitivity for late-onset sepsis diagnosis (65%) which was statistically superior to CRP (49%, p < 0.001) and CBC (49%, p < 0.001) alone." (PMID 29382319, 2018). "We aimed to evaluate the diagnostic utility of the C-Reactive protein (CRP) and the complete blood count (CBC) for late-onset sepsis in VLBW infants." (PMID 29382319, 2018). "Necrotizing enterocolitis (NEC) shares similar manifestations with neonatal sepsis, including increased CRP levels, making it difficult to distinguish from sepsis." (PMID 30094238, 2018). "Currently, biomarkers such as: Pro-BNP, lactate, CRP, D-Dimer, Pro-Calcitonin and Troponin are considered for determining the prognosis of patients with sepsis." (PMID 29503829, 2018). "Diagnosis is optimised by using biochemical tests for sepsis, such as C - reactive protein (CRP) or leukocyte count (WBC) which have reportedly low diagnostic accuracy and are at times ambiguous." (PMID 30319777, 2018). "For proven sepsis, the cut-off level of CRP was found to be 2.6 mg/L with 70.4% sensitivity, 83.0% specificity, 64.5% PPV and 86.4% NPV." (PMID 30068303, 2018). "The cut-offs of CRP were determined to be 0.58 mg/dL and 0.48 mg/dL for proven sepsis and all sepsis, respectively." (PMID 30068303, 2018). "CRP was reported in ours study because this biomarker was routinely measured on a daily basis for patients with sepsis." (PMID 30254204, 2018). "Of interest in the present context is a study in 94 patients with sepsis or septic shock in two hospitals in Brazil in which either CRP or PCT was reported to be effective for guiding therapy and reducing antibiotic use." (PMID 30332466, 2018).
Sepsis (continued). "In EONS, we found the cut-off level of CRP 1 for the diagnosis of sepsis to be 2.6 mg/L with a 80.6% sensitivity, 83.0% specificity, 67.5% PPV and 90.7% NPV." (PMID 30068303, 2018). "For proven sepsis, the cut-off of CRP 1 was 7.0 mg/L with a 76.5% sensitivity, 98.2% specificity, 94.9% PPV and 90.5% NPV (p < 0.001)." (PMID 30068303, 2018). "For proven sepsis, the cut-off level of the CRP 1 was 7.0 mg/L with 76.5% sensitivity, 98.2% specificity, 94.9% PPV and 90.5% NPV according to the ROC curves (p < 0.001)." (PMID 30068303, 2018). "Between 2012 and 2015, PCT use among sepsis discharges increased six-fold while lactate and CRP use remained unchanged." (PMID 30332466, 2018). "Since the majority of clinicians include a CBC in the initial workup of suspected late-onset sepsis, it is unlikely that an approach solely based on serial CRP measure would be adopted." (PMID 29382319, 2018). "C-reactive protein can also be an indicator of organ failure and therefore has potential for the surveillance of sepsis severity." (PMID 30446841, 2018). "Area under curve (AUC) of PCT and AUC of CRP were higher than AUC of MPV in the study sepsis subgroups." (PMID 30068303, 2018). "A total of 250 critically ill pediatric patients diagnosed with sepsis were retrospectively analyzed to identify routinely measured predictors for in-hospital mortality at the peak level of C-reactive protein." (PMID 30446841, 2018). "For the diagnosis of clinical sepsis, at the CRP 1 cut-off of 2.6 mg/L, the sensitivity, specificity, PPV and NPV were 73.6, 83.0, 67.2 and 86.9% respectively." (PMID 30068303, 2018). "The CRP/albumin ratio was initially developed to predict clinical outcome and complications in patients with severe medical illness, such as sepsis; after that, it was also indicated to predict prognosis in some cancer patients." (PMID 30258731, 2018). "Blood samples were collected within the first few hours of the onset of clinical sepsis (CRP 1, PCT 1, MPV 1) and were repeated after 24 h (CRP 2, PCT 2, MPV 2)." (PMID 30068303, 2018). "For examples, patients with sepsis or septic shock had higher value of CRP/ALB ratio as a cut-off value than in our study." (PMID 29495423, 2018). "The median CRP level was 47.8 mg/dl (10.2-119.5) in the sepsis group and 18.6 mg/dl (4.9-66.1) in the non-sepsis group (p=0.006)." (PMID 30190753, 2018). "At T0, combining the CBC and the CRP had the highest sensitivity of 66% (95% confidence interval [CI], 58–73) compared to both individual tests for predicting late onset sepsis." (PMID 29382319, 2018). "This study assessed the ability of mid-regional proadrenomedullin (MR-proADM) in comparison to conventional biomarkers (procalcitonin (PCT), lactate, C-reactive protein) and clinical scores to identify disease severity in patients with sepsis." (PMID 29562917, 2018). "For the first time, we demonstrated that PCT, sTREM-1, CRP and IL-6 were predictors of severe sepsis on the third day of SI; the PCT level had the highest AUC (0.744), with a sensitivity of 79% and a specificity of 63% at a cut-off value of 1.7 ng/ml." (PMID 29282483, 2018). "Their general information, vital signs, and blood index including serum procalcitonin (PCT) and C-reactive protein (CRP) levels at admission, diagnosis of sepsis, and 1-week post-diagnosis of sepsis were compared." (PMID 30397617, 2018). "The aim of the present study was to investigate the ability of NLR and MPV in differentiating sepsis from non infectious causes of SIRS and to compare them with the traditional parameters CRP and PCT." (PMID 30190753, 2018). "A study in Netherlands in 2012 indicated the higher power of this scale compared to biomarkers such as CRP and Lactate in prediction of 28-day mortality of sepsis patients in ED." (PMID 29503829, 2018). "Though PCT is superior to CRP and other traditional biomarkers of sepsis in critical practice, it is inaccurate for clinicians to judge clinical conditions." (PMID 29137405, 2017).
Sepsis (continued). "The ROC analysis showed that hs-CRP was a good marker that discriminated septic shock patients from sepsis patients, with an AUC of 0.751 (95% CI: 0.62-0.88; P = 0.002)." (PMID 28764651, 2017). "Overall, the median CRP ranged from 62 to 73 mmol/L, which suggests that lactate concentrations were measured during periods of acute illness and likely sepsis." (PMID 28432751, 2017). "Nonetheless, these cytokines are typically increased very rapidly during neonatal sepsis, even more so the well-known proinflammatory marker C-reactive protein." (PMID 28367457, 2017). "Interactions between platelet P2Y12 inhibitors and the immune system result in both favorable, including reduced incidence of sepsis and pulmonary adverse events, and adverse, including elevation of CRP and dyspnea, effects." (PMID 28056791, 2017). "In this work, we examined the ability of mid-regional proadrenomedullin (MR-proADM) in predicting mortality in sepsis patients with different degrees of organ failure, compared to that of procalcitonin, C-reactive protein and lactate." (PMID 28185230, 2017). "We also evaluated some clinical parameters associated AGI, such as AGI type (primary or secondary), GI surgery, serum albumin, sepsis, serum C-reactive protein, serum procalcitonin, arterial lactate, catecholamine support, SOFA score, APACHE II score, and IAP." (PMID 28356059, 2017). "Clinical sepsis was defined by the maximal C-reactive protein (CrP) exceeding 20 mg/L within the first 72 h of life." (PMID 28046032, 2017). "C-reactive protein (CRP) and procalcitonin were used to help predict mortality risk in patients with sepsis." (PMID 28320333, 2017). "In this study, we found that hs-CRP was as good as PCT for the diagnosis of sepsis and septic shock among the oldest old patients." (PMID 28764651, 2017). "Our data indicates that cytokine profiles provide valuable information for neonatal sepsis therapy and are even more informative when compared with routine CRP and lymphocyte numbers assessment." (PMID 28367457, 2017). "C-reactive protein (CRP) is widely used as an indicator of infection, but it reacts too slowly for prognostic use at the early stages of sepsis." (PMID 28845081, 2017). "To investigate a possible use of CT-proET-1 in identifying patients with sepsis, we conducted a ROC curve analysis comparing CT-proET-1 to other, established markers (procalcitonin and C-reactive protein (CRP))." (PMID 28331622, 2017). "Procalcitonin (PCT), neutrophil-lymphocyte count ratio (NLCR), C-reactive protein (CRP), and lactate were determined in a total of 1,572 episodes of adult patients admitted to the emergency department on suspicion of sepsis." (PMID 28727802, 2017). "The C-reactive protein/albumin ratio (CRP/Alb), consisting of CRP and albumin, was initially used to assess the outcome of patients with acute medical admissions and sepsis." (PMID 28431566, 2017). "The sensitivity of CRP in diagnosing sepsis was 98.03%, specificity was 91.0%, positive predictive value (PPV) was 97% and negative predictive value (NPV) was 93.7%." (PMID 29492073, 2017). "Several studies have suggested maternal serum CRP concentration of 8 mg/L as a cutoff value for infection-related complications such chorioamnionitis, funisitis, and early-onset sepsis." (PMID 28813455, 2017). "In our cohort, we indeed observed clear associations with sepsis, IL6, CRP, and other inflammation-related biomarkers." (PMID 29180833, 2017). "If the physician classifies the child as having severe illness, they will collect a blood specimen for blood culture (using BACTEC) and a sepsis screen (CRP, TLC, differential count, and band cell:neutrophil count ratio) as soon as possible." (PMID 28359325, 2017). "The aim of this study was to evaluate sCD14 as a predictor of the progression of febrile neutropenia to sepsis and its complications and to compare sCD14 with other sepsis biomarkers such as CRP and PCT in hematological patients." (PMID 28845081, 2017).
Sepsis (continued). "TLC, differential count and CRP will be captured as part of the sepsis screen in babies with clinical severe illness." (PMID 28359325, 2017). "Procalcitonin (PCT) and high-sensitivity C-reactive protein (hs-CRP) are the most frequently used biomarkers for critically ill patients in whom sepsis is suspected." (PMID 28764651, 2017). "Among 9 recipients with both high CRP and low albumin levels, 4 recipients had neutrophil counts equal to or exceeding 500/μl at the onset of bacteremia, and 8 recipients had severe sepsis or septic shock." (PMID 28938875, 2017). "Muller and colleagues conducted a study in consecutive critically ill patients to compare the usefulness of serum concentration of calcitonin precursor, CRP, IL-6 and lactate for the diagnosis of sepsis." (PMID 28794881, 2017). "Serum levels of sTREM-1, IL-6, PCT, and CRP were significantly higher in patients with septic shock than in those with severe sepsis." (PMID 28380034, 2017). "Despite its potential role as a biomarker of infection, few studies have assessed the usefulness of CRP in the diagnosis of sepsis after abdominal surgery in critically ill patients 18,19." (PMID 28226029, 2017). "We hereby performed this study to compare the efficacy of PCT and hs-CRP in the diagnosis of sepsis and septic shock in oldest old patients." (PMID 28764651, 2017). "We performed a systematic review and meta-analysis of the available literature to assess the accuracy of presepsin for the diagnosis of sepsis in adult patients and compared the performance between presepsin, C-reactive protein (CRP), and procalcitonin (PCT)." (PMID 28875483, 2017). "Sepsis biomarkers, including procalcitonin and CRP, showed a significantly higher discriminatory capacity for these classification tasks." (PMID 28079172, 2017). "A serial blood test of CRP in previous study demonstrated the peak level of CRP was within 24-48 h during sepsis." (PMID 28764651, 2017). "A polymicrobial sepsis with ConS, E. faecalis, K. oxytoca and E. cloacae was detected in one episode with a maximum CRP at 10.5 mg/dL." (PMID 29117261, 2017). "The infant was again evaluated with total leucocyte count, absolute neutrophil count, CRP, blood culture and chest radiograph and was started on antibiotic (piperacillin–tazobactum) in suspicion of late onset sepsis (LOS)." (PMID 28061799, 2017). "It was identified that initial neonatal sepsis onset (within the first 24 hours of infection) was best diagnosed with a combination of IL-6 and CRP detection, with a cutoff of 18 pg/mL for IL-6 and 10 pg/mL for CRP (sensitivity: 89%; specificity: 73%)." (PMID 28487810, 2017). "CRP on the other hand provides a slow kinetic profile, which explains the superior discrimination between surgical and sepsis patients, since blood samples of surgical patients were drawn immediately after admission to Intensive Care Unit (ICU)." (PMID 28472045, 2017). "They found sensitivity of CRP only 40.0% in first 24 hours of sepsis and 90.0% after 24 hours of infection." (PMID 29492073, 2017). "They observed 75% of diagnostic accuracy, 72% of specificity and sensitivity of 76% for PCT and concluded that PCT is superior to CRP in terms of accuracy in identification and assessment of severity of sepsis." (PMID 28794881, 2017). "These authors thus found NLR as a more convenient marker for infection than CRP, with a high specificity (83.9%) but a moderate sensitivity for diagnosing septicemia in critically ill patients." (PMID 27995553, 2017). "Median CRP values were highest in the group of term newborns with sepsis and in patients with NEC (52.1 (1-3Q: 15.8–94.1) and 22.8 (1-3Q: 6.1–59.1) mg/dl, resp)." (PMID 28769143, 2017). "The levels of leukocytes, blood lactate, and CRP were significantly higher in patients with sepsis than in the SIRS and control groups." (PMID 29463949, 2017). "A major CRP response is observed in infection and sepsis, various auto-immunopathies, tissue necrosis, trauma, and neoplasia." (PMID 29058588, 2017).